FRG1 (FSHD region gene 1)
Description:
Binds to mRNA in a sequence-independent manner. May play a role in regulation of pre-mRNA splicing or in the assembly of rRNA into ribosomal subunits. May be involved in mRNA transport. May be involved in epigenetic regulation of muscle differentiation through regulation of activity of the histone-lysine N-methyltransferase KMT5B.
Synonyms: FSG1; FRG1A
Tractability: Small molecule: a structure with a bound ligand is known. PROTAC: ubiquitination databases record sites on it; its protein half-life has been measured.
Gene: Protein-coding gene on chromosome 4 (189,940,842 to 189,963,207, forward strand). Ensembl gene ENSG00000109536.
Subcellular location: Nucleus, Cajal body; Nucleus, nucleolus; Cytoplasm; Cytoplasm, myofibril, sarcomere, Z line
Gene Ontology:
Molecular function: protein binding; RNA binding; actin filament binding
Biological process: mRNA splicing, via spliceosome
Cellular component: catalytic step 2 spliceosome; cytoplasm; spliceosomal complex; U2-type catalytic step 1 spliceosome; nucleolus; striated muscle dense body; Cajal body; Z disc
Genetic constraint (gnomAD): Loss-of-function variants: 6 observed, 15.46 expected, observed/expected ratio (o/e) 0.39, 90% interval 0.21 to 0.77. The upper end of that interval is the gene's LOEUF score, 0.77, which puts it in group 3 of 6, group 1 being the genes least tolerant of losing a copy. Missense variants: 111 observed, 132.77 expected, observed/expected ratio (o/e) 0.84, 90% interval 0.72 to 0.98. Synonymous variants: 38 observed, 44.73 expected, observed/expected ratio (o/e) 0.85, 90% interval 0.65 to 1.11.
Homologues: Orthologues: chimpanzee FRG1 (100% identical), dog FRG1 (99% identical), macaque FRG1 (99% identical), rabbit FRG1 (98% identical), guinea pig FRG1 (97% identical), mouse Frg1 (97% identical), rat Frg1-ps1 (95% identical), tropical clawed frog frg1 (81% identical), rat Frg1 (80% identical), zebrafish frg1 (77% identical), Drosophila melanogaster FRG1 (48% identical), Caenorhabditis elegans frg-1 (45% identical).
Diseases named in the same sentence as FRG1 in open-access papers:
FRG1 is named in the same sentence as 36 diseases in open-access papers, as found by Europe PMC text mining. Sharing a sentence is not in itself a finding about the gene and the disease. The quoted sentences say what the papers report.
facioscapulohumeral muscular dystrophy (19 papers, 2004 to 2025). An autosomal dominant disorder affecting the skeletal muscles of the face, scapula, and upper arm. "The contraction of the macro-satellite repeats in DUX-pseudogenes and centromeric deletion involving the FRG1 gene were reported as a cause of muscular dystrophy in general and facioscapulohumeral muscular dystrophy in particular." (PMID 31784692, 2019). "FSHD region gene 1 (FRG1), which was first identified as a candidate gene for facioscapulohumeral muscular dystrophy (FSHD), has been reported to have a role in muscle development." (PMID 36815234, 2023). "FSHD region gene 1 (FRG1), which is mainly known for being the candidate gene for facioscapulohumeral muscular dystrophy (FSHD), has recently shown its potential as a tumor suppressor gene." (PMID 36329016, 2022). "FRG1 is a candidate gene responsible for facioscapulohumeral muscular dystrophy and it is critical for muscle development." (PMID 34828393, 2021). "FRG1 is a candidate gene for Facioscapulohumeral muscular dystrophy (FSHD) but it has also been shown to affect vasculature." (PMID 30975102, 2019). "FSHD region gene 1 (FRG1) is an evolutionarily conserved protein, associated with the inherited muscle disease Facioscapulohumeral muscular dystrophy (FSHD)." (PMID 25695429, 2015). "The Frg1 gene is inappropriately overexpressed in facioscapulohumeral muscular dystrophy and thought to function in mRNA splicing." (PMID 24520355, 2014). "Overexpression of Frg1, a gene whose expression is altered in facioscapulohumeral muscular dystrophy, results in aberrant alternative pre-mRNA splicing associated with a muscular dystrophy phenotype in transgenic mice." (PMID 24520355, 2014). "The subtelomeric region of 4q is also interesting because it contains a candidate gene, FRG1, for facioscapulohumeral muscular dystrophy." (PMID 15310400, 2004). "The FSHD region gene 1 (FRG1) is the primary candidate gene for facioscapulohumeral muscular dystrophy (FSHD)." (PMID 40282371, 2025). "Facioscapulohumeral muscular dystrophy (FSHD) region gene 1 (FRG1) is a candidate gene for FSHD." (PMID 28947680, 2017). "The distal portion of the human 4q35 genomic region (4q35.2) contains a complex arrangement of repetitive sequences and several genes including facioscapulohumeral muscular dystrophy (FSHD) region genes 1 and 2 (FRG1 and FRG2)." (PMID 17359533, 2007). "Recent study shows that FRG1 (GMI value 2.07, up-regulated in group {1, 4, 3}) a multifunctional protein, specially binds to F-actin and its misregulation leads to facioscapulohumeral muscular dystrophy (FSHD)." (PMID 21909426, 2011).
muscular dystrophy (10 papers, 2009 to 2021). Muscular dystrophy (MD) refers to a group of more than 30 genetic diseases characterized by progressive weakness and degeneration of the skeletal muscles that control movement. "The FRG1 over-expressing mouse is a transgenic mouse characterized by strong up-regulation of human FRG1, causing muscular dystrophy similar to FSHD (abnormal spinal curvature, progressive muscle dystrophy, skeletal muscle atrophy, differential involvement of muscle types similar to FSHD)." (PMID 22912879, 2012). "In summary, our experiments have demonstrated the expression of FRG1 in mouse muscle causes a tissue-specific and age-dependent proliferative defect in the satellite cell population, possibly playing a part in the development of muscular dystrophies and FSHD in humans." (PMID 21603621, 2011). "Overexpression of FRG1 disrupts the organization and integrity of the musculature in other model organisms and muscle from FRG1 overexpressing mice show features of muscular dystrophy." (PMID 26942723, 2016). "FRG1-transgenic mice develop a muscular dystrophy phenotype that shares key histological and physiological features with FSHD including, abnormal curvature of the spine (kyphosis) and skeletal muscle atrophy involving characteristic FSHD affected muscles." (PMID 25695429, 2015). "Here we addressed two key questions; does a myoblast fusion defect contribute to the pathogenesis of muscular dystrophy observed in FRG1-transgenic mice and if so, does enhanced myoblast fusion rescue the dystrophic phenotype." (PMID 25695429, 2015). "This excluded the possibility that most of the splicing alterations identified in FRG1 mice were simply due to a common molecular phenotype found in all muscular dystrophies." (PMID 23300487, 2013). "In contrast to transgenic mice overexpressing FRG2 or ANT1, only transgenic mice overexpressing FRG1 appear to have symptoms characteristic of muscular dystrophy." (PMID 21603621, 2011). "Importantly, our study reveals that FHL1, a positive regulator of muscle hypertrophy and myoblast fusion, reduces muscle wasting and improves the muscular dystrophy phenotype observed in FRG1 mice by rescuing the FRG1-induced myoblast fusion defect." (PMID 25695429, 2015). "Transgenic mice overexpressing FRG1 recapitulate the FSHD muscular dystrophy phenotype." (PMID 25695429, 2015). "Collectively, these findings indicated that FRG1 over-expression induced a characteristic set of splicing changes that can be observed in both cultured muscle cells and in tissues, and is distinct from that observed in a different model of muscular dystrophy." (PMID 23300487, 2013). "Among those genes, FRG1 was recently shown to be involved in muscle development in Xenopus, and transgenic mice that strongly over-express FRG1 in their skeletal muscles present a muscular dystrophy, suggesting an involvement in the disease." (PMID 19829708, 2009). "Therefore, to provide proof of principle that FRG1 can impair myoblast fusion leading to muscular dystrophy, we investigated if co-expression of an agent that promotes myoblast fusion could rescue the dystrophic phenotype of FRG1 mice." (PMID 25695429, 2015). "Therefore, increased FRG1 expression may contribute to a muscular dystrophy phenotype resembling FSHD by impairing myoblast fusion, a defect that can be rescued by enhanced myoblast fusion via expression of FHL1." (PMID 25695429, 2015). "In addition, Rbfox1 was expressed at normal levels in mdx mice, indicating that its down-regulation in FRG1 mice is not generally associated with muscular dystrophy." (PMID 23300487, 2013). "Regardless of whether the levels of FRG1 are increased or not in FSHD patients, the H-FRG1TG mouse is a valuable tool for studying the mechanics of muscular dystrophy, though it is important to note that FRG1 expression in these mice is many fold higher than observed in any human patients." (PMID 21603621, 2011).
prostate carcinoma (7 papers, 2019 to 2025). A carcinoma that arises from epithelial cells of the prostate gland. "Additional variants were found in TACC2, a centrosomal protein important for mitotic spindle formation, and FRG1, a gene implicated in muscle and vascular development as well as prostate cancer." (PMID 41488087, 2025). "We previously reported that reduction of FRG1 is associated with increased p38‐MAPK signaling in prostate cancer and with elevated MEK–ERK signaling in breast cancer." (PMID 36815234, 2023). "Our study first time revealed FRG1 expression level and localization in prostate cancer tissue and, showed the significant loss of FRG1 expression in tumor tissues." (PMID 30975102, 2019). "Additionally, reduced FRG1 expression has been linked to prostate cancer progression, as well as alterations in prostate cancer cell migration and invasion." (PMID 37021811, 2023). "In prostate cancer, depleted FRG1 levels increased cell proliferation, migration, and invasion via activation of the p38‐MAPK pathway." (PMID 36815234, 2023). "Depletion of FRG1 levels increased cancerous properties of prostate cancer cell lines via activation of the p38-MAPK." (PMID 36329016, 2022). "Reduced expression of FRG1 has been frequently observed in prostate cancer tissue, which contributes to tumor progression through the p38-MAPK pathway." (PMID 34571936, 2021). "Depletion of FRG1 led to increased tumorigenic properties in prostate cancer cell lines and activation of p38 MAPK (mitogen-activated protein kinase) signaling." (PMID 34795329, 2021). "There was a highly significant difference in the survival probability between high and low FRG1 expression groups in cervix, stomach, and prostate cancers." (PMID 34795329, 2021). "In prostate cancer tissue, FRG1 levels were significantly reduced, compared to the uninvolved counterpart." (PMID 30975102, 2019). "Oncomine datamining, in our previous work, showed the reduced expression of FRG1 in more studies, which includes prostate cancer." (PMID 30975102, 2019). "In this study we used three different prostate cancer lines to establish role of FRG1 with respect to androgen receptor status and varying invasiveness." (PMID 30975102, 2019). "FRG1 expression was analyzed in prostate cancer by immunohistochemistry in 20 needle core biopsies along with tissue array, consisting of 180 cores (including 90 paired tumor and uninvolved tissue)." (PMID 30975102, 2019). "On the contrary, in our data FRG1 knockdown enhanced cell migration in prostate cancer cells in vitro." (PMID 30975102, 2019). "Overall, the effect exerted by FRG1 on prostate cancer cell properties and expression of various cytokines is mediated via p38 MAPK activity." (PMID 30975102, 2019). "Our group showed FRG1-mediated activation of the p38-MAPK pathway in prostate cancer." (PMID 36329016, 2022). "Previously we found enhanced GM-CSF expression in FRG1-depleted prostate cancer cells." (PMID 36329016, 2022). "In this study, we investigated the role of FRG1 in prostate cancer progression." (PMID 30975102, 2019). "Up-regulation of GM-CSF with FRG1 knockdown in prostate cancer cells might be one of the factors affecting cell migration and invasiveness." (PMID 30975102, 2019). "Therefore, we intend to understand the etiological function of FRG1 in prostate cancer." (PMID 30975102, 2019). "Here we report that FRG1 knockdown leads to p38 activation in prostate cancer cells affecting CXCL1 expression, which is well supported by previous studies, except the role of FRG1." (PMID 30975102, 2019). "FRG1 expression levels are reduced in prostate tumor tissue and its expression affects the cell migratory and invasiveness properties of AR negative prostate cancer cell lines." (PMID 30975102, 2019).
prostate carcinoma (continued). "To figure out if the effect of FRG1 expression on prostate cancer cells is irrespective of androgen receptor status, we used LNCaP cell lines with ectopic expression of FRG1 and depletion of FRG1 along with their controls, for cell based assays." (PMID 30975102, 2019). "FRG1 expression affects migration and invasion in AR negative prostate cancer cells through known MMPs and cytokines, which may be mediated primarily via p38 MAPK activation." (PMID 30975102, 2019).
breast carcinoma (6 papers, 2017 to 2024). "In the current study, our findings first-ever report the inverse association of FRG1 expression levels with breast cancer and unravel the underlying molecular mechanism using multiple model systems." (PMID 36329016, 2022). "Furthermore, survival analysis in GEPIA and Kaplan–Meier plotter designates the association of high FRG1 level with a higher recurrence-free survival rate in breast cancer patients, indicating a favorable role of FRG1 towards prognosis determination." (PMID 36329016, 2022). "MTS and transwell migration assays were performed to elucidate the effect of altered FRG1 expression in breast cancer cells on endothelial cell proliferation and migration." (PMID 36815234, 2023). "Mechanistically, FRG1 depletion activated the expression of FGF2 in breast cancer cells, which triggered the ERK/AKT cascade in endothelial cells." (PMID 36815234, 2023). "The graphical representation shows that the depletion of FRG1 in breast cancer cells enhances the level of FGF2." (PMID 36815234, 2023). "In conclusion, the reduction in FRG1 increases FGF2 expression in breast cancer cells, which activates angiogenic properties of endothelial cells via AKT‐ERK signaling." (PMID 36815234, 2023). "Overall, here we report the role and molecular mechanism of a new gene, FRG1, in breast cancer, which has the potential to be explored as a therapeutic target irrespective of molecular subtypes." (PMID 36329016, 2022). "The present study first time, discovered the in-depth role of GM-CSF in breast cancer and found that FRG1 acts as its repressor." (PMID 36329016, 2022). "Intrigued by the effect of FRG1 expression level on the tumorigenic properties of breast cancer cells, we explored its effect on ERK and AKT, two frequently altered signaling pathways in cancers." (PMID 36329016, 2022). "Our findings first time elucidate the role of FRG1 as a metastatic suppressor of breast cancer by regulating the GM-CSF/MEK-ERK axis." (PMID 36329016, 2022). "To validate our findings, we performed a retrospective study in clinical patient samples and found reduced FRG1 expression in 71% of breast cancer patients' tissues." (PMID 36329016, 2022). "In our case, we have found that reduced FRG1 expression led to the activation of ERK in both the breast cancer cell lines." (PMID 36329016, 2022). "Expression profiling of the genes associated with triple-negative breast cancer (TNBC) using the MDA-MB-231 cell line showed FRG1 as one of the significantly downregulated genes which were connected with the migratory potential of breast cancer cells." (PMID 36329016, 2022). "To further authenticate TCGA dataset-based findings, we collected 194 breast cancer tissue samples with 56 normal adjacent tissues and performed IHC for FRG1 expression." (PMID 36329016, 2022). "To identify novel contributors and molecular subtype independent therapeutic options, we report reduced expression of FRG1 in breast cancer patients, which regulates GM-CSF expression via direct binding to its promoter." (PMID 36329016, 2022). "Together these data suggest FRG1 expression can modulate the tumorigenic properties of breast cancer cell lines." (PMID 36329016, 2022). "To investigate the therapeutic potential of anti-GM-CSF therapy in breast cancer patients with reduced FRG1 expression, we did a mouse model-based study." (PMID 36329016, 2022). "In conclusion, reduced expression of FRG1 in breast cancer leads to transcriptional activation of GM-CSF, which promotes activation of ERK and EMT." (PMID 36329016, 2022). "Taken together the in vitro and in vivo data, the therapeutic potential of FRG1-mediated signaling can be explored in all molecular subtypes of breast cancer." (PMID 36329016, 2022).